PTX3 (pentraxin 3)
Diseases named in the same sentence as PTX3 in open-access papers (continued):
Sharing a sentence is not in itself a finding about the gene and the disease.
glioma (continued). "PTX3 protein expression was validated via immunohistochemistry in 56 glioma specimens." (PMID 40656950, 2025). "Future research should focus on the functional role of PTX3 and its interactions within the glioma microenvironment, which could lead to novel therapeutic strategies for improving patient management based on its expression profile." (PMID 40656950, 2025). "Overall, these pathways not only illuminate the molecular mechanisms through which PTX3 may influence glioma biology but also underscore its potential as a therapeutic target for the development of more effective treatment strategies." (PMID 40656950, 2025). "Understanding the role of PTX3 in glioma progression is crucial, as it could inform the development of personalized treatment strategies and improve patient outcomes in this complex disease context." (PMID 40656950, 2025). "The correlation between PTX3 and neutrophil infiltration suggests that PTX3 may influence neutrophil behavior in the glioma microenvironment, potentially affecting tumor dynamics and patient prognosis." (PMID 40656950, 2025). "In the high-grade glioma tissue, PTX3 was expressed by both tumor cells and activated macrophages." (PMID 41373493, 2025). "Clinicopathological characteristics of glioma patients with high- and low-PTX3 expression levels." (PMID 40656950, 2025). "Previous research has demonstrated the critical role of IL-18 in the tumor immune microenvironment, suggesting that PTX3 may be crucial in modulating the immune response in glioma." (PMID 40656950, 2025). "In conclusion, this research aims to address the existing gap in PTX3 studies related to glioma by employing diverse bioinformatics techniques to explore its role in glioma progression, thus providing new insights and evidence for potential therapeutic strategies." (PMID 40656950, 2025). "In this context, the upregulation of PTX3 may enhance immune cell recruitment and activation, thereby modulating the immune environment in glioma and providing a rationale for immune-modulatory therapeutic strategies." (PMID 40656950, 2025). "Increased expression of PTX3 was negatively correlated with B cell activation, proliferation, and the expression level of IgG, which indicated inhibited humoral immunity, confirming the role of PTX3 in regulating immune infiltrating cells in glioma." (PMID 38730589, 2024). "However, in other contexts (i.e. glioma, head and neck cancers, hepatocellular carcinoma) PTX3 overexpression has a pro-tumorigenic effect, promoting cell invasion or proliferation and epithelial to mesenchymal transition." (PMID 37025408, 2023). "PTX3 is required for maintaining the autophagic flux in gliomas." (PMID 37476290, 2023). "The transcription factor ZNF148 promotes the malignant transformation of dendritic cells after cross‐talk with glioma stem cells by upregulating PTX3, and reduce the expression of co‐stimulatory factors on the surface of DCs, inhibit their antigen presentation and activation of T cells." (PMID 37063077, 2023). "Additionally, recurrent and secondary gliomas expressed higher PTX-3 levels in comparison with primary ones." (PMID 36499628, 2022). "Glioma samples from the Xiangya cohort were divided into two groups based on the H‐scores of PTX3." (PMID 35855654, 2022). "We observed that the high expression of PTX3 was related to the unmethylated gliomas." (PMID 35855654, 2022). "This meant that PTX3 could serve as a predictor for determining the severity and survival rate of patients with gliomas." (PMID 35855654, 2022). "PTX3 had relatively higher expression in recurrent and secondary gliomas than primary gliomas." (PMID 35855654, 2022). "During tumourigenesis, elevated PTX3 levels have been detected in various cancers, including liposarcoma, glioma, ovarian cancer, lung cancer, pancreatic carcinoma, prostate carcinoma and hepatocellular carcinoma, and are correlated with the grade of malignancy and a poor prognosis." (PMID 35090088, 2022).
glioma (continued). "The receiver operating characteristic curve (ROC) analysis further indicated that PTX3 expression could predict IDH mutation in LGG and pan‐glioma samples in the CGGA dataset (the AUC value = 0.756, 0.656, respectively)." (PMID 35855654, 2022). "Notably, down‐regulation of PTX3 leads to the inhibition of tumor growth and development, while up‐regulation of PTX3 promotes the proliferation and invasion of glioma cells." (PMID 35855654, 2022). "Even more, through immunochemistry analysis, Locatelli and colleagues correlated malignancy with higher levels of PTX-3 glia-localized, produced by infiltrated macrophages in specimens collected from 63 patients diagnosed with primary central nervous system tumors." (PMID 36499628, 2022). "In glioma, the expression of PTX3 is increased along with the tumor grade elevated (P < 0.001)." (PMID 32984316, 2020). "PTX3 expression in glioma is higher than normal tissue (P < 0.001)." (PMID 32984316, 2020). "However, the relationship between PTX3 expression, clinical factors, and prognosis in glioma remains unclear, warranting further investigation to clarify its role in cancer progression." (PMID 40656950, 2025). "have identified that PTX3 plays a crucial role in glioma cell proliferation and invasion, and may thus serve as a novel potential therapeutic target in the treatment of gliomas; it is related to the recurrence of glioma." (PMID 37091145, 2023). "Besides, the ROC curve indicated that PTX3 expression could predict IDH mutation in LGG and pan‐glioma samples in the TCGA dataset (the AUC value = 0.901 and 0.824, respectively)." (PMID 35855654, 2022). "Besides, SPOCD1 promotes the metastasis and proliferation of glioma cells via PTX3." (PMID 35646092, 2022). "Thus, PTX3 acts as a prognostic prediction biomarker of glioma." (PMID 32984316, 2020). "Interestingly, PTX3 overexpression was frequently observed in high-grade gliomas and meningiomas with poor prognosis, which suggests that PTX3 may be an important contributor to meningioma cell proliferation and invasion." (PMID 32983987, 2020). "PTX3 promotes the transcription and secretion of periostin (POSTN), which triggers activation of the MAP-ERK, which promotes EMT-like processes in glioma cells." (PMID 39201656, 2024). "Thus, the pathway blockage of PTX3-POSTN-MAPK may be beneficial in patients with gliomas." (PMID 39201656, 2024). "PRMT1 mediated epigenetic modification H4R3me2a not only plays an essential role in PTX3 expression, but PRMT1 potentiated the ability of PTX3 to sensitize glioma cells to ferroptosis inducer." (PMID 37476290, 2023). "We demonstrate for the first time that PRMT1/H4R3me2a differentially regulates PTX3-driven ferritinophagic flux in IDH1 wild-type and mutant gliomas." (PMID 37476290, 2023). "This correlation of PRMT1 and PTX3 with ferritinophagic markers is conserved in gliomas of diverse genetic landscape and shows prognostic value in IDH1 mutant glioma patients." (PMID 37476290, 2023). "PTX3 is a component of the glioma microenvironment, being generated by tumor cells and infiltrating CD68-positive macrophages, and local PTX3 levels are correlated with grade and malignancy." (PMID 37091145, 2023). "The top 20 network analysis indicated that PTX3, TIMP1, CHI3L1, LTF and IGFBP3 comprise a crucial role in gliomas progression." (PMID 36153549, 2022). "Combined with our previous result, the OS, PFI, and DSS of LGG, GBM, and pan‐glioma patients with high expression of PTX3 were significantly lower than that of LGG, GBM, pan‐glioma patients with low expression of PTX3, respectively." (PMID 35855654, 2022). "In our research, PTX3 is highly correlated with PD‐1, PD‐L1, CD274, CD276, and HAVCR2, all of which can mediate immune escape of gliomas." (PMID 35855654, 2022). "PTX3 expression in CL and ME subtypes was significantly higher than NE and PN subtypes in LGG and pan‐glioma from the TCGA dataset." (PMID 35855654, 2022).
glioma (continued). "Our results highlighted the role of PTX3 and TIMP1 which were previously considered in glioma tumorigenesis as well as LTF as a new potential biomarker." (PMID 36153549, 2022). "Immunohistochemistry was used to assess PTX3 expression, HAVCR2, PD‐1, PD‐L1, and CD276 in glioma sections from the Xiangya cohort (n = 60)." (PMID 35855654, 2022). "Based on the five independent prognostic factors (PTX3 expression, age, 1p19q status, IDH status, and the grade of gliomas), we built a predictive model by nomogram in the TCGA dataset." (PMID 35855654, 2022). "The area under the receiver operating characteristic curve (AUC) values of PTX3 in predicting CL and ME subtypes were 92.1% and 95.0% in LGG and pan‐glioma from the TCGA dataset, respectively." (PMID 35855654, 2022). "Based on the TCGA and CGGA datasets, we proved that PTX3 positively correlated with CD276, CD274, PDCDL1LG2, HAVCR2, CD80, IDO1, and PDCD1 in pan‐glioma, GBM, and LGG." (PMID 35855654, 2022). "To the survival significance of the CARD-associated genes, we investigated the protein level of one of the four genes, PTX3, in 103 IDH-wt glioma samples from the SYSUCC corhort by using TMA and IHC methods." (PMID 33796538, 2021). "The 89-gene signature consists of a number of hypoxia and inflammation-related genes such as AKR1C3, PTX3, PLAT and IGFBP2, showing that these two inseparable hallmarks are involved in tumor progression and play significant roles in glioma pathogenesis." (PMID 27323413, 2016). "Furthermore, BMP2, NCF1, HSPB1, PIGT, PTX3, CCNA2, and CCNB2 exhibited increased expression, while DES displayed decreased expression in glioma tissues." (PMID 40656950, 2025). "Combined with PTX3 regulation, targeting the PI3K-Akt pathway may offer a novel approach to enhance therapeutic efficacy in glioma patients." (PMID 40656950, 2025). "PTX3 is an important component of the GBM microenvironment that is produced by both tumor cells and infiltrating CD68‐positive macrophages, and local PTX3 levels correlate with glioma grade and malignancy." (PMID 37063077, 2023). "There is clear evidence that PTX3, TIMP1, and TUBA1C are related to glioma invasion." (PMID 37091145, 2023). "Additionally, in glioma samples from the TCGA and CGGA datasets, PTX3 expression was generally up‐regulated in patients with 1p/19q non‐codeletion." (PMID 35855654, 2022). "In this study, the ROC curves further confirmed that PTX3 with the AUC values of 92.1% and 95.0% in LGG and Pan‐glioma could be a sensitive marker of the CL and ME subtypes." (PMID 35855654, 2022). "E2F7, PTX3, and VAV3 have been reported as oncogene in many kinds of tumors especially in glioma." (PMID 34222249, 2021). "Additionally, the results showed that elevated PTX3 expression was associated with reduced survival rates in patients with G4, IDH wild-type, 1p/19q non-codel in patients diagnosed with glioma." (PMID 40656950, 2025). "Interestingly, PTX3 has also been identified as a downstream target by which the spen paralogue and orthologue C-terminal (SPOC) domain-containing 1 (SPOCD1) genes exert their cancerous effects in gliomas." (PMID 38730589, 2024). "However, the immune‐modulatory role of PTX3 in the tumor microenvironment of glioma has not been elucidated." (PMID 35855654, 2022). "However, the immune characteristics and clinical significance of PTX3 have not been adequately elucidated in gliomas." (PMID 35855654, 2022). "Several pathways or molecules have been incriminated in gastric cancer development; however, the connection with PTX-3 serum levels has not yet been realized in comparison with other types of cancer (such as prostate and breast tumors, colorectal cancer, and gliomas)." (PMID 36499628, 2022).
glioma (continued). "The correlation between CRNDE gene and PTX3 and STX1A genes has not been correlated for the time being confirmation in the literature, but PTX3 has been shown to be associated with poor prognosis in gliomas, and in connection with our results, its upstream target marker may be the CRNDE gene." (PMID 33767729, 2021).
lung carcinoma (39 papers, 2012 to 2025). "reinforced the diagnostic potential of serum PTX3 in lung cancer and demonstrated that high interstitial PTX3 expression in resected tumor specimens correlates with poor prognosis, indicating shorter survival." (PMID 41479916, 2025). "Increased PTX-3 synthesis by lung cancer stem cells predisposes to invasive and metastatic properties." (PMID 36499628, 2022). "In this study, we investigated the utility of pentraxin 3 (PTX-3) in bronchoalveolar lavage fluid (BALF) as lung cancer (LCa) diagnostic." (PMID 32587638, 2020). "The PTX-3 in BALF showed a diagnostic advantage in lung cancer diagnosed with a larger area under the curve (0.949)." (PMID 32587638, 2020). "Immunohistochemical analysis on tissue specimens from lung cancer revealed an interstitial expression of PTX3 in the neoplastic area associated with shorter survival, while no staining was observed in normal lung parenchyma." (PMID 31019517, 2019). "PTX3 is an inflammatory factor involved in fertility and also, its overexpression has been associated to lung cancer." (PMID 25887408, 2015). "Moreover, PTX3 has been identified as an effective marker to differentiate between lung cancer patients and individuals at high risk for the disease." (PMID 41479916, 2025). "In addition, extensive research highlights the clinical relevance of PTX3 as both a diagnostic and prognostic marker in lung cancer." (PMID 41479916, 2025). "Serum PTX3 serves as a novel and informative diagnostic biomarker for lung cancer." (PMID 41479916, 2025). "Furthermore, elevated PTX3 levels in lung cancer patients with COPD were associated with worse progression-free survival (PFS)." (PMID 41479916, 2025). "Furthermore, the upregulation of PTX3 induced by gemcitabine treatment has been linked to increased aggressiveness of lung cancer cells through the NF-κB signaling pathway." (PMID 41479916, 2025). "Furthermore, it has been suggested that PTX3 is an informative serum biomarker of lung carcinoma, being highly expressed in high risk lung cancer patients and over-expressed in human soft tissue liposarcoma and prostate tumor." (PMID 24457902, 2014). "In addition, ROC analysis indicated that PTX3 could discriminate between cancer patients and heavy smokers at high risk for lung cancer." (PMID 31019517, 2019). "Specifically, both PTX3 deglycosylation and PTX3 knockdown via AKT/NF-κB signaling inhibition have been shown to suppress tumor growth, enhancing the susceptibility of lung cancer cells to cisplatin treatment." (PMID 41479916, 2025). "Both studies highlight the role of PTX3, an inflammatory factor, as a potential biomarker in lung cancer." (PMID 41479916, 2025). "Deglycosylation of PTX3 by tunicamycin inhibits growth and migration of lung cancer cells, and sensitizes lung cancer to cisplatin through AKT/NF-κB signaling inactivation." (PMID 41479916, 2025). "PTX3 is significantly higher in squamous cell carcinoma cell lines, as well as in the serum of lung cancer patients compared to healthy individuals." (PMID 41479916, 2025). "Among the studies mentioned, a significantly higher level of PTX3 was found in patients with COPD compared to lung cancer patients." (PMID 41479916, 2025). "Peripheral PTX3 levels are higher in COPD patients than in lung cancer patients, while in lung cancer patients with COPD, an elevated PTX3 level is associated with worse PFS." (PMID 41479916, 2025). "PTX3 has emerged as a potential effector in lung cancer treatment, particularly in combination with cisplatin." (PMID 41479916, 2025). "Gemcitabine induces PTX3 upregulation via NF-κB signaling pathway, leading to augmented invasiveness of lung cancer cell, which is inhibited by Rg3." (PMID 41479916, 2025). "Subsequent validation confirmed that serum PTX3 levels are significantly elevated in lung cancer patients compared to healthy individuals, but still lower than in patients with chronic obstructive pulmonary disease (COPD)." (PMID 41479916, 2025).
lung carcinoma (continued). "Peripheral PTX3, correlated with shorter OS, is elevated in lung cancer via AKT/NF-κB signaling, while its silencing overcomes cisplatin resistance in NSCLC cells." (PMID 41479916, 2025). "Serum PTX3 is higher in lung cancer patients than in heavy smokers, whereas high local PTX3 expression in tumors independently correlates with shorter survival." (PMID 41479916, 2025). "This was further corroborated by findings showing upregulated PTX3 levels in bronchoalveolar lavage fluid from lung cancer patients, particularly those with SCLC or obstructive pneumonia." (PMID 41479916, 2025). "PTX3 was reported to have the potential for predicting prognosis as well as immunotherapy response in lung cancer." (PMID 39308671, 2024). "Multiple pathways mediate Cis resistance in lung cancer; one is the glycosylated form of long pentraxin-3 (PTX3) overexpression in lung cancer cells." (PMID 38474359, 2024). "Overexpression of PTX3 is related to poor prognosis in lung cancer patients via a local inflammatory response." (PMID 37063077, 2023). "In patients with lung cancer, prostate cancer or colorectal carcinoma, blood PTX3 levels resulted elevated compared respectively to healthy subjects, patients with prostatic inflammation or colorectal polyps." (PMID 37025408, 2023). "PTX3 has been studied as an emerging biomarker reflecting tissue injuries and inflammation, such as lung carcinoma and heart failure." (PMID 37957139, 2023). "Nevertheless, PTX-3 can also be overexpressed in lung cancer cells and other pulmonary inflammatory diseases (such as bronchitis, asthma, and COPD)." (PMID 36499628, 2022). "In conclusion, PTX-3 serum and tissular levels represent valuable targets in lung cancer prognosis and diagnosis." (PMID 36499628, 2022). "It was reported that PTX3 is related to various cancers such as prostate cancer and lung cancer 25-28." (PMID 33967610, 2021). "The protein expression of HGF, PTX3, and S100P in lung cancer tissues and normal lung tissues was validated using the HPA online database." (PMID 34745947, 2021). "At the cutoff point of 1952.3828 pg/mL for PTX-3 levels, the sensitivity for the diagnosis of lung cancer with obstructive pneumonia was 88.00% and the specificity was 80.00%." (PMID 32587638, 2020). "PTX3 was recognized by proteomics as a critical candidate biomarker for liposarcoma, lung cancer, prostate cancer, and pancreatic cancer." (PMID 31334115, 2019). "PTX-3 levels were found statistically significantly higher in patients with lung cancer and/or aged above 65 years." (PMID 31086534, 2019). "day 3 PTX-3 levels of patients with lung cancer were found statistically significantly higher compared with the pre-op." (PMID 31086534, 2019). "In the 110 patients of this cohort that developed resectable lung cancer, preoperative PTX3 plasma levels were higher compared with those of cancer-free heavy smokers, but were not predictor of outcomes." (PMID 31019517, 2019). "It was subsequently observed that PTX3 circulating levels were related to disease aggressiveness and progression, irrespective to the subtypes and histotypes of lung cancer." (PMID 31019517, 2019). "High PTX3 levels have been shown to correlate with unfavorable outcome in several conditions such as cardiovascular diseases, lung cancer and polymyalgia rheumatica." (PMID 23341967, 2013). "Notably, the upregulated PTX3 levels in bronchoalveolar lavage fluid also serve as a biomarker for lung cancer, particularly in small cell lung cancer (SCLC) and in cases with obstructive pneumonia." (PMID 41479916, 2025). "However, a study showed that TM treatment sensitizes the Cis effect on lung cancer cells, mediated via the deglycosylation of PTX3 through the AKT/NF-κB signaling pathway." (PMID 38474359, 2024).